PALM (paralemmin)
Description:
Involved in plasma membrane dynamics and cell process formation. Isoform 1 and isoform 2 are necessary for axonal and dendritic filopodia induction, for dendritic spine maturation and synapse formation in a palmitoylation-dependent manner.
Synonyms: KIAA0270; PALM1
Tractability: Antibody: UniProt places it where antibodies can reach, with high confidence; its Gene Ontology location is reachable by antibodies, with high confidence; the Human Protein Atlas places it where antibodies can reach. PROTAC: ubiquitination databases record sites on it; its protein half-life has been measured.
Gene: Protein-coding gene on chromosome 19 (708,935 to 748,329, forward strand). Ensembl gene ENSG00000099864.
Subcellular location: Cell membrane; Cell projection, filopodium membrane; Cell projection, axon; Cell projection, dendrite; Cell projection, dendritic spine; Basolateral cell membrane; Apicolateral cell membrane
Subcellular location (Human Protein Atlas): Nucleoplasm; Plasma membrane
Gene Ontology:
Molecular function: protein binding; cytoskeletal protein-membrane anchor activity; D3 dopamine receptor binding; protein-membrane adaptor activity
Biological process: negative regulation of dopamine receptor signaling pathway; positive regulation of filopodium assembly; adenylate cyclase-inhibiting G protein-coupled receptor signaling pathway; synapse maturation; cellular response to electrical stimulus; protein localization to plasma membrane; regulation of cell shape
Cellular component: filopodium membrane; nucleoplasm; plasma membrane; cytoplasmic side of plasma membrane; cytoplasmic vesicle; filopodium; neuron spine; postsynapse; synaptic membrane; apicolateral plasma membrane; axon; basolateral plasma membrane; cytoplasm; dendrite; dendritic spine; membrane; postsynaptic density
Genetic constraint (gnomAD): Loss-of-function variants: 14 observed, 22.92 expected, observed/expected ratio (o/e) 0.61, 90% interval 0.4 to 0.95. The synonymous counts are far from expectation, so gnomAD's model fits this gene poorly and the ratio says little. Missense variants: 528 observed, 515.13 expected, observed/expected ratio (o/e) 1.02, 90% interval 0.95 to 1.1. Synonymous variants: 286 observed, 229.46 expected, observed/expected ratio (o/e) 1.25, 90% interval 1.13 to 1.38.
Homologues: Orthologues: chimpanzee PALM (99% identical), macaque PALM (94% identical), pig PALM (84% identical), dog PALM (83% identical), mouse Palm (80% identical), rat Palm (79% identical), tropical clawed frog palm (52% identical), zebrafish palm1a (50% identical), zebrafish palm1b (32% identical). Paralogues in human: PALMD (32% identical), PALM3 (22% identical), PALM2AKAP2 (21% identical).
Diseases named in the same sentence as PALM in open-access papers:
PALM is named in the same sentence as 12 diseases in open-access papers, as found by Europe PMC text mining. Sharing a sentence is not in itself a finding about the gene and the disease. The quoted sentences say what the papers report.
breast carcinoma (2 papers, 2012 to 2023). "Paralemmin-1 mRNA levels were higher in breast cancers than in RM tissue and estrogen receptor (ER)-positive tumors had higher transcript levels than ER-negative tumors." (PMID 22574838, 2012). "The major difference between paralemmin-1 staining in normal breast tissue (RM) and breast cancer (DCIS and IDC) was the greater frequency of strong staining in cancer tissue." (PMID 22574838, 2012). "Our discovery of paralemmin-1 overexpression in breast cancer cell lines came from a cDNA array comparison between the ER-positive breast cancer cell line, MCF-7, and its tamoxifen-selected, ER-negative derivative, TMX2-28.." (PMID 22574838, 2012). "We found paralemmin-1 to be more frequently expressed in breast cancers than in reduction mammoplasty tissues and more highly expressed in ER-positive breast cancer as compared to ER-negative cancers." (PMID 22574838, 2012). "Three of the six breast cancer lines examined expressed moderate to high levels of paralemmin-1 mRNA, whereas levels in the three others were low or undetectable." (PMID 22574838, 2012). "Here we show for the first time that paralemmin-1 is expressed in breast cancer cell lines and human breast cancers." (PMID 22574838, 2012). "In a global gene expression comparison between two breast cancer cell lines, paralemmin-1 was over expressed in the invasive, estrogen-receptor (ER) negative breast cancer cell line (TMX2-28) as compared to the non-invasive ER-positive parent cell line (MCF-7)." (PMID 22574838, 2012). "The differential expression of paralemmin-1 in a subset of breast cancers suggests the existence of variation in membrane dynamics that may be exploited to improve diagnosis or provide a therapeutic target." (PMID 22574838, 2012). "Given the function of paralemmin-1 in plasma membrane dynamics and cell motility in fibroblasts, we hypothesized that paralemmin-1 may play a role in the invasive growth that accompanies metastasis of breast cancers." (PMID 22574838, 2012). "A cDNA microarray comparison between the ER-positive MCF-7 breast cancer cell line and its tamoxifen-selected, ER-negative derivative, TMX2-28, had shown that paralemmin-1 mRNA was more highly expressed (8 times greater) in TMX2-28 cells than in MCF-7 cells." (PMID 22574838, 2012). "Examination of cellular protein by Western Blot analysis using paralemmin-1 antibody revealed differences between breast cancer and non-tumorigenic cell lines." (PMID 22574838, 2012). "Real time RT-PCR demonstrated that paralemmin-1 mRNA levels were higher in breast cancer cell lines than in non-tumorigenic breast cell lines." (PMID 22574838, 2012). "Therefore, to investigate the relationship between paralemmin-1 expression and ER status, in the present study we examined the expression of paralemmin-1 in additional breast cancer and non-tumorigenic breast cell lines." (PMID 22574838, 2012). "Paralemmin-1 was upregulated in androgen-independent relative to both androgen-dependent tumors and to normal controls in a mouse prostate model, and high levels of paralemmin-1 and paralemmin-2-AKAP2 expression were correlated with an invasive morphological phenotype of breast cancer cell lines." (PMID 22574838, 2012).
breast tumors (1 paper, 2012). "Here we examine the mRNA and protein expression of paralemmin-1 and its splice variants in ER-positive and ER-negative breast cell lines, primary breast tumors and tissue from reductive mammoplasty surgeries." (PMID 22574838, 2012). "In the present report we not only found that paralemmin-1 expression was greater in a subset of breast tumors, but also that paralemmin-1 expression was greater in tumor tissues than in RM tissues." (PMID 22574838, 2012). "Furthermore, when we examined RNA levels in 26 primary breast tumors we found paralemmin-1 expression to be significantly higher in ER-positive as compared to ER-negative tumors." (PMID 22574838, 2012).
cognitive decline (1 paper, 2024). "Seven of the 22 peptides associated with the frail vs control diagnostic contrast and cognitive decline were cytoskeleton-related, including proteoforms of MAP2, VIM, TUBB, DBN1, TUBA8, PALM and NEFM." (PMID 38531951, 2024).
ductal carcinomas in situ (1 paper, 2012). "Paralemmin-1 protein expression was examined in cell lines using Western Blots and in 31 ductal carcinomas in situ, 65 infiltrating ductal carcinomas, and 40 RM tissues using immunohistochemistry." (PMID 22574838, 2012).
cancer (4 papers, 2012 to 2023). A tumor composed of atypical neoplastic, often pleomorphic cells that invade other tissues. "Both splice variants of paralemmin-1 (65/55 kDa; +/− exon 8) were detected in variable proportions in the cancer cell lines." (PMID 22574838, 2012). "PALM is a protein implicated in plasma membrane dynamics, the development of filopodia, neurites, and dendritic spines, and the invasive and metastatic potential of cancer cells." (PMID 37328063, 2023). "Paralemmin-1 is a protein implicated in plasma membrane dynamics, the development of filopodia, neurites and dendritic spines, as well as the invasiveness and metastatic potential of cancer cells." (PMID 22855693, 2012). "Among the six cancer cell lines examined, paralemmin-1 mRNA levels were highest in the ER-negative cell line, TMX2-28." (PMID 22574838, 2012). "In two reports paralemmin-1 was identified through mRNA microarray analyses as being upregulated in cancer cells." (PMID 22574838, 2012). "There have been only a few reports of paralemmin-1 expression in cancer tissue." (PMID 22574838, 2012). "These properties of paralemmin-1 might implicate this protein not only in normal morphogenesis but also abnormal development and cancer." (PMID 22574838, 2012). "At present we do not know whether normal tissue adjacent to the cancer expresses paralemmin-1 or the Δ exon 8 splice variant." (PMID 22574838, 2012). "Of the four non-cancer cell lines, only one (MCF-10A) had detectable levels of paralemmin-1 transcript." (PMID 22574838, 2012).
infection (2 papers, 2016 to 2025). The state of being infected such as from the introduction of a foreign agent such as serum, vaccine, antigenic substance or organism. "Depletion of the Plasmodium-specific apicoplast protein (PALM) results in defects in liver merozoite formation in vitro and impaired initiation of a blood-stage infection." (PMID 27353755, 2016). "In a study, the loss of apicoplast protein PALM resulted in parasite attenuation in the liver-stage that further failed to develop into merozoites and did not initiate blood-stage infection." (PMID 39714137, 2025).
tumor (2 papers, 2012 to 2025). "A previous study showed that PALM is expressed in lymphatic endothelial cells and is closely associated with tumor lymphangiogenesis." (PMID 40533863, 2025). "Paralemmin-1 splice variants were assessed in tumor and RM tissues using a series of primers and RT-PCR." (PMID 22574838, 2012). "In this study, by combining TCGA analysis with the assessment of PALM expression in CC cell lines, we found that PALM acts as a tumor suppressor gene." (PMID 40533863, 2025). "In this study we focused on evaluating paralemmin-1 staining characteristics of benign epithelial cells in RM and tumor epithelial cells." (PMID 22574838, 2012). "Use of laser-capture microdissection to isolate RNA from tumor and adjacent benign tissue may be valuable in defining the expression and role of paralemmin-1 in breast carcinogenesis." (PMID 22574838, 2012). "Furthermore, the identification of this ceRNA mechanism not only offers novel insights into the progression of CC but also underscores circ-NOLC1 as a potential prognostic biomarker and therapeutic target for restoring PALM-dependent tumor-suppressive functions in CC." (PMID 40533863, 2025).
PALM also shares sentences with these, for which no sentence is quoted: cervical cancer (1 paper); colon cancer (1); epilepsy (1); infiltrating ductal carcinomas (1); prostate carcinoma (1).